Y_RNA (Y RNA )
Gene: Miscellaneous RNA gene on chromosome 3 (45,903,187 to 45,903,298, forward strand). Ensembl gene ENSG00000201635.
Homologues: Orthologues: chimpanzee Y_RNA (100% identical), macaque Y_RNA (81% identical). Paralogues in human: Y_RNA (85% identical), RNY1 (84% identical), Y_RNA (82% identical), Y_RNA (81% identical), Y_RNA (80% identical), RNY1P5 (79% identical), Y_RNA (79% identical), RNY1P2 (79% identical), RNY1P7 (79% identical), Y_RNA (78% identical), RNY1P11 (77% identical), RNY1P9 (77% identical), and 91 more.